BRAF (B-Raf proto-oncogene, serine/threonine kinase)
Diseases named in the same sentence as BRAF in open-access papers (continued):
Sharing a sentence is not in itself a finding about the gene and the disease.
colorectal cancer (continued). "Subsequently, the positive results from the BEACON CRC (colorectal cancer) trial led the FDA to approve, in 2020, the combination of encorafenib and cetuximab (an anti-EGFR monoclonal antibody) in the setting of pretreated BRAF V600E mutant patients with metastatic colorectal cancer." (PMID 36230797, 2022). "The relationship between BRAF and p21 genes can be observed in the KEGG colorectal cancer pathway." (PMID 34836311, 2021). "Moreover, therapeutic experiences clearly indicated that hEx3, unlike conventional anti-EGFR antibodies, was effective against colorectal cancer (CRC) cells with mutant KRAS, BRAF, or PIK3CA." (PMID 32666260, 2021). "A limiting factor in using BRAF inhibitors is that BRAF inhibitors are unlikely to work on patients with colorectal cancers that have normal BRAF genes." (PMID 34440099, 2021). "AREG reversed the inhibitory effects of cetuximab in RAS/BRAF wild-type cetuximab-naïve colorectal cancer cells, but not in cetuximab-resistance cells in vitro." (PMID 34893673, 2021). "In addition, these data lacked the description of the distant metastasis site and the detection of key molecules of colorectal cancer, like KRAS and BRAF." (PMID 32469151, 2020). "Preclinical and clinical studies showed that the lack of efficacy of single-agent BRAF (encorafenib) or dual BRAF and MEK inhibition (encorafenib plus binimetinib) in BRAF V600E-mutated colorectal cancer is related to rapid EGFR-mediated adaptive feedback." (PMID 32933095, 2020). "Co-occurrence of mutations at positions 594 and 600 of BRAF is not found, but D594 (D594N) mutation and a concomitant NRAS G13V mutation has been identified in colorectal cancer." (PMID 33198372, 2020). "In addition, cartridges that are able to detect the most relevant genetic alterations of both the BRAF and NRAS genes in a single assay are now available, and they can be also used in other tumors harboring such alterations (i.e., colorectal cancer)." (PMID 32751423, 2020). "In another report, the same dual β1-integrin/EGFR inhibition approach, as well as KRAS or BRAF depletion and 5-FU-treatment failed to modulate the radiosensitivity of colorectal carcinoma cells." (PMID 32903756, 2020). "Although we conducted four human colorectal cancer cell lines in this experiments, did not confirm other human colorectal cancer cell lines harboring KRAS, BRAF and PIK3CA mutation and patients-derived MEK inhibitor resistance colorectal cancer cells." (PMID 31769426, 2019). "To date, due to their rarity, the BRAF mutant/MSS colorectal cancers have not been as thoroughly studied as BRAF/MSI cancers." (PMID 31455041, 2019). "We found that there was inconsistency in the frequency distribution of CNAs in both of the data sets for those actionable genes from our list which are considered promising druggable targets for NSCLC, and colorectal cancer, such as KRAS, BRAF, EGFR, ATM, and PIK3CA." (PMID 30728399, 2019). "The effect was independent of tissue type as it was also observed in a BRAF-mutant colorectal cancer cell line." (PMID 31727958, 2019). "However, EGFR remains a valid target in colorectal cancer within the population of patients wild-type for KRAS, NRAS, and BRAF, with proven clinical benefit." (PMID 29254887, 2018).
colorectal cancer (continued). "As the finding indicated that the efficacy of “cetuximab after oxaliplatin” was not restricted to the KRAS/BRAF wild-type background, the experiment was repeated using a panel of seven other colorectal cancer cell lines, representing variable KRAS/BRAF genotypes." (PMID 30410004, 2018). "The benefit of utilizing BRAF inhibitors does not apply to colorectal cancer due to the rapid feedback activation of EGFR." (PMID 30519549, 2018). "The genotypic frequencies of MLH1 retained BRAF mutant colorectal cancers was not significantly different from the control cohort." (PMID 29304767, 2018). "At the molecular level, the Lynch syndrome is distinguished by sporadic MSI-high colorectal cancers because acquired CpG methylation of the MLH1 promoter and V600E mutation of the BRAF gene are frequently observed in the latter, but not in the former." (PMID 29652830, 2018). "Our findings indicate there are several histological patterns of OM in colorectal cancer, and that OM has no relation to NRAS and BRAF mutation." (PMID 29029440, 2017). "However, many cancers, such as colorectal cancers, contain KRAS/BRAF mutant genes and are resistant to MEKi, BRAFi, or RTKis treatments." (PMID 28002807, 2017). "We further analyzed the association of EZH2 expression with the efficacy of anti-EGFR therapy in patients with colorectal cancer with no mutations in KRAS (codon 61/146), NRAS (codon 12/13/61), or BRAF (codon 600)." (PMID 28147317, 2017). "Together, we showed feedback HER3 activation upon cetuximab treatment in KRAS and BRAF colon cancer cells together with induction of HER2:HER3 heterodimers, which could potentially result in cetuximab resistance in colorectal cancer patients." (PMID 28032592, 2017). "The fact that STK11ex1-2 mutations were also associated with KRAS mutations might be related to a shared risk factor (tobacco) or an oncogenic cooperation between both alterations as for BRAF or KRAS with PIK3CA in lung and colorectal cancer." (PMID 26625312, 2017). "Despite promising data, the clinical use of any biomarker in general practice is lacking, and currently only KRAS, BRAF and microsatellite instability are currently used in the diagnosis and treatment of colorectal cancer." (PMID 28125730, 2017). "Furthermore, specific BRAF-fusions are common across multiple adult and pediatric cancers, including KIAA1549-BRAF found in pediatric gliomas, breast carcinoma, and sarcomas, and MKRN1-BRAF in PLGGS, colorectal carcinoma, and head and neck carcinoma." (PMID 29156677, 2017). "Colorectal SRCC has more frequent BRAF mutations and MLH1 loss, less frequent 18q LOH, and lower COX2 levels, when compared with non-SRCC colorectal cancer." (PMID 27994618, 2016). "BCL2 family inhibitors, in combination with a TORC1/2 inhibitor, lead to apoptosis in KRAS- and BRAF-mutants but not wild-type (WT) colorectal cancer cells." (PMID 26636651, 2015). "BRAF mutations, which are perhaps one of the most commonly accepted indicator events for CIMP in colorectal cancers, also appear to be relevant in LUAD, but not the other tumor types." (PMID 25960768, 2015). "Furthermore, a patient with a BRAF V600E-mutant, wt KRAS colorectal cancer, with a history of early progression to cetuximab-based therapy, was found to have a KRAS G12D mutation (24.39%) in cfDNA instead, which was not previously detected in the tumor tissue." (PMID 25980577, 2015). "In colorectal cancer, CIMP tumors had distinct epidemiologic characteristics, microsatellite instability (MSI) profile BRAF mutations and survival, compared to non-CIMP tumors." (PMID 26098903, 2015). "In conclusion, the RALA pathway impinges on the transcription of a distinct subset of target genes in colorectal cancer cells independent of the KRAS and BRAF mutational status." (PMID 26033452, 2015).
colorectal cancer (continued). "Of note is that hereditary non-poliposis colorectal carcinomas (HNPCC) generally do not exhibit BRAF mutations, therefore it might be tested to exclude such a hereditary form of CRC." (PMID 26220423, 2015). "Other biomarkers used to help treatment decisions in colorectal cancer include the use of KRAS mutation status as a predictive marker and the use of BRAF mutations as a strong negative prognostic indicator in KRAS wild-type colorectal cancer." (PMID 25566504, 2014). "This is similar to Grivennikov and colleagues who report an upregulation of IL-23 in early cancers but no further increase in expression in more advanced mouse colorectal cancers caused by Apc loss and forced KRAS or BRAF activation." (PMID 25015728, 2014). "In a cellular context, we used the human colorectal cancer cell lines HT29 and HCT116 identified without any mutation in KRAS and BRAF." (PMID 24618737, 2014). "In BRAF mutant colorectal cancer it has been learned that negative feedback pathways are stimulated by the constitutive activation of the MAPK pathway conferred by BRAF activating mutations and that these pathways act to diminish signaling through the EGFR." (PMID 25520658, 2014). "With only BRAF gene study, it was not possible to identify any correlation with family history of colorectal cancer." (PMID 24759670, 2013). "Two studies detected the critical role of EGFR in BRAF V600E mutant colorectal cancer cells that did not respond to BRAF inhibition." (PMID 24298448, 2013). "TRAIL sensitivity was not related to the presence of activating oncogenic KRAS, BRAF and PIK3CA mutations common to colorectal cancer." (PMID 23852390, 2013). "Retrospective analyses in the West suggest that mutations in KRAS codons 61 and 146, BRAF, NRAS, and PIK3CA are negative predictive factors for cetuximab treatment in colorectal cancer patients." (PMID 24006859, 2013). "In contrast to KRAS, the heterogeneity of BRAF and PIK3CA mutations has not been adequately investigated in colorectal cancer thus far." (PMID 22931052, 2012). "Colorectal cancer has previously been split into at least three groups based on methylation profiles: non-CIMP tumors, CIMP-high tumors associated with BRAF mutations and CIMP-low mutations associated with KRAS mutations." (PMID 23034185, 2012). "Among the 13 patients with V600K BRAF mutation, eight received RAF/MEK targeting agents (of which one was colorectal cancer), three did not receive treatment (only best palliative care) and two received other targeting agents." (PMID 22039425, 2011). "Colorectal cancers lacking oncogenic alterations in genes encoding EGFR downstream effectors such as KRAS, BRAF, PIK3CA, and PTEN have the highest probability of response to anti-EGFR therapies." (PMID 22152101, 2011). "Recently a number of randomized trials have shown that patients with advanced colorectal cancer do not benefit from therapies targeting the epidermal growth factor receptor when their tumors harbor mutations in the KRAS, BRAF and PIK3CA genes." (PMID 20098682, 2010). "Finally, the integration of CDX2 with molecular biomarkers such as MSI, RAS, BRAF, or SATB2 may lead to the development of comprehensive prognostic and predictive models, supporting a more personalized therapeutic approach in colorectal cancer." (PMID 41388313, 2025). "Given the considerable genetic and molecular diversity among BRAF-V600E mutant colorectal cancers, these results may not fully capture the variability present in broader clinical populations." (PMID 40678543, 2025).
colorectal cancer (continued). "Similarly, the addition of ribavirin enhanced the efficacy of MEK inhibitor cobimetinib against xenografts of BRAF-mutant colorectal carcinoma RKO, even though ribavirin alone had no discernible effect on survival." (PMID 41465386, 2025). "Researchers have discovered many genes related to the occurrence and development of colorectal cancer through genomic studies, including but not limited to the PIK3CA, KRAS, APC, SMAD4, and BRAF genes, among which the PIK3CA gene has attracted widespread attention." (PMID 39555098, 2024). "In colorectal cancer, KRAS mutation has been reported as an unfavorable prognosis factor, though the literature data are somewhat mixed likely due at least in part to the presence/absence of the adjustment for a strong confounder variable, BRAF mutation." (PMID 39039804, 2024). "Interestingly, the analysis of immune cell populations suggests a propensity for neutrophil recruitment to BRAF/KRAS mutant CRLM in the absence of APC mutations, corroborating observations from serrated colorectal cancer murine models in human patients." (PMID 37057593, 2023). "Although several studies demonstrated that MSI-H, BRAF mutation, MLH1 hypermethylation, or CIMP-high, characteristics shared with CMS1 colorectal cancer were associated with high levels of Fn infection, none of these studies showed any association between Fn infection and KRAS mutations." (PMID 37772997, 2023). "This problem is evident in colorectal cancer, in which, despite the advances in therapeutic options, such as EGFR inhibitors and drug combinations using EGFR inhibitor plus VEGF inhibitor/MEK inhibitor/BRAF inhibitor, the mortality rate remains high for cancer-related deaths." (PMID 37049976, 2023). "BRAF mutant-type colorectal cancer does not benefit from cetuximab therapy." (PMID 36212504, 2022). "Moreover, it is expected that additional vulnerabilities that are not revealed with the approach used here exist in BRAF mutant colorectal cancers." (PMID 36295658, 2022). "On the other hand, Zecchin and colleagues clearly demonstrated that proteasome inhibitors possess a significant selectivity toward BRAFV600E-mutant colorectal cancer cells as a consequence of persistent BRAF signaling and a nononcogenic addiction to the proteasome function in those cells." (PMID 33467521, 2021). "Whereas, different from other studies that NTRK gene rearrangements are highly enriched in RAS wild-type colorectal carcinomas, there were only two classical fusion cases harboring KRAS (n = 1) and NRAS (n = 1) mutations; but no BRAF mutation cases were in our study." (PMID 33996597, 2021). "However, the general strategy of targeting RAF dimerization in RAS/RAF mutant colorectal cancers is unlikely to qualitatively transform the outcomes with targeted therapies without appropriate attention to the unique biology of BRAF and KRAS mutant CRC." (PMID 32922659, 2020). "To examine the basal levels of autophagy in colorectal cancer (CRC) cell lines, we selected the human RKO cell line and primary SW480 and its derivative metastatic SW620 cell lines as representative of a range of BRAF-driven and KRAS-driven colorectal genotypes, respectively." (PMID 31151160, 2019). "However, colorectal cancers harboring constitutive activating mutations in KRAS, NRAS and BRAF genes are not responsive to anti-EGFR therapy." (PMID 31711486, 2019). "In a large cohort of 85 patient-derived colorectal cancer xenografts, Bertotti and colleagues identified HER2 gene amplification in some xenografts, which were resistant to cetuximab and did not harbour mutations in KRAS, NRAS or BRAF genes." (PMID 31164152, 2019).
colorectal cancer (continued). "However, similarly positive responses were not seen when advanced BRAF mutant colorectal cancer patients were treated with vemurafenib." (PMID 30598662, 2018). "However, for patients with early-stage colorectal cancers, the overall survival between BRAF mutant and wild-type cancers differed non-significantly." (PMID 29652830, 2018). "A large body of literature demonstrated that colorectal cancer patients with non-MSI-high and mutant BRAF were associated with the highest mortality, whereas patients with MSI-high/BRAF-wild-type showed the lowest mortality when both MSI and BRAF mutation status were considered." (PMID 28623901, 2017). "Taken together, our results indicate that the dysregulation of miR-193a-3p is involved in the tumorigenesis of colorectal cancer, particularly BRAF-mutant cancer, and is likely to affect drug sensitivities to anti-EGFR therapy in colorectal cancer regardless of BRAF mutational status." (PMID 29115941, 2017). "We found that BRAF V600E mutation was present as follows: sporadic MSI-colorectal cancers 17/33 (51%) (result was not available for 7), sporadic MSS- colorectal cancers 0/40 (0%) (result was not available for 3), and Lynch syndrome-colorectal cancers 0/15 (0%) (result was not available for 12)." (PMID 27047543, 2016). "Multivariate analysis showed that NDRG4 could be a prognostic factor for overall survival of patients with colorectal cancer independent of gender, age, differentiation status, TNM stage, KRAS, BRAF and PIK3CA mutations and MSI status." (PMID 26515606, 2016). "In addition, a patient with prostate carcinoma (BRAF V600E mutation by the CLIA, but not Idylla) and colorectal cancer (BRAF V600E mutation by the Idylla, but not CLIA) never received BRAF or MEK inhibitors." (PMID 26330075, 2015). "Hence, the RALA pathway-responsive gene signature identified in the three colorectal cancer cell lines comprises 554 genes, irrespective of the mutational status of KRAS or BRAF." (PMID 26033452, 2015). "Multivariate analysis showed that NEAT1 expression could be a prognostic factor for overall survival of patients with colorectal cancer independent of gender, age, differentiation status, TNM stage, MSI, KRAS, BRAF and PIK3CA mutation." (PMID 26314847, 2015). "BRAF and EGFR (epidermal growth factor receptor) genes, which are important co-factors of KRAS gene in the EGFR signaling pathway in the carcinogenesis, invasion and metastasis of colorectal cancers, also have prognostic value for patients with metastasis of adenocarcinoma." (PMID 25297496, 2014). "This is the first report of KRAS and BRAF status in Albanian patients with colorectal carcinoma (CRC) and though the relatively small sample size might not provide enough statistics power." (PMID 25267307, 2014). "The recognition that colorectal cancer (CRC) is a heterogeneous disease in terms of clinical behaviour and response to therapy translates into an urgent need for robust molecular disease subclassifiers that can explain this heterogeneity beyond current parameters (MSI, KRAS, BRAF)." (PMID 23836465, 2013). "It has also been speculated that colorectal cancer patients with the BRAF mutant type may be considered to be a minor 'non-effective' group for cetuximab therapy as determined by clinical trials." (PMID 21554739, 2011). "KRAS codon 12/13 and 59/61 and BRAF V600E mutations, MSI, and MGMT and hMLH1 methylation and expression in 42 serrated adenocarcinomas and 17 serrated adenomas were compared with those in 59 non-serrated colorectal carcinomas (CRCs) and nine adenomas." (PMID 21457162, 2011). "Recently a number of randomized trials have shown that treatment of patients with advanced colorectal cancer (CRC) do not benefit from therapies targeting the epidermal growth factor receptor (EGFR) when their tumors harbor mutations in the KRAS, BRAF and PIK3CA genes." (PMID 20098682, 2010).